LPL (lipoprotein lipase)
Diseases named in the same sentence as LPL in open-access papers (continued):
Sharing a sentence is not in itself a finding about the gene and the disease.
infection (continued). "qRT‐PCR analysis revealed that lenti‐shZFP36L1 infection remarkably decreased ZFP36L1 mRNA expression which resulted in significant up‐regulation of the mRNA levels of the adipogenic differentiation markers (PPARγ, PLIN1, LPL and FABP4) as compared with the lenti‐control (lenti‐ctrl) infection." (PMID 29993187, 2018). "Infection of LPL cKO Tva mice with RCAS-LPL retroviruses by tail vein injection yielded no detectable hLPL immunoreactivity in isolated myofibers or significant changes in serum triglyceride levels 2 weeks post-infection (data not shown)." (PMID 29304082, 2018). "Before infection, C2C12 showed similar LPL activity both inside the cells and on the cell surface; 3T3L1 showed more intracellular LPL activity than at the cell surface, while HEK293T only showed intracellular LPL activity." (PMID 28969646, 2017). "Our observations suggest that LPL neither destroyed the virus particles nor induced their internalization into structures likely to direct the virus to abortive infection." (PMID 22039521, 2011). "qRT‐PCR analysis revealed that lenti‐shPPARGC1B infection significantly decreased PPARGC1B mRNA expression, which resulted in significant down‐regulation of the mRNA levels of the adipogenic differentiation markers (PPARγ, PLIN1, LPL and FABP4) as compared with the lenti‐ctrl infection." (PMID 29993187, 2018). "Since we planned to express LPL by infection of differentiated striated muscle tissue, we assessed whether single muscle fibers (myofibers) isolated from LPL cKO Tva mice were competent for RCAS infection, integration, and expression of hLPL." (PMID 29304082, 2018). "In the absence of LPL, the virions were detected within cells as soon as 5 min after infection." (PMID 22039521, 2011). "Our control experiments excluded the possibility of a direct virolytic effect of LPL on HCV: the infectious potential of JFH-1 was not significantly decreased by incubation of the virus preparation with 1 μg/ml LPL in vitro for 4 h at 37°C before infection)." (PMID 22039521, 2011). "These analyses clearly demonstrated a progressive increase of the number of intracellular gold-labeled core particles (from T0 to T20 min post infection) with respect to the number of particles located outside the cell when infection was carried out in the absence of LPL." (PMID 22039521, 2011). "Despite all these differences in density, LPL inhibited the infection of cells by all virus populations, regardless of whether the viruses were produced in vitro or in vivo." (PMID 22039521, 2011). "We used primary human umbilical vein endothelial cells (HUVEC) as a heterologous cell model that contains PPARδ but does not express HL or LPL to test whether VLDL regulates ADRP gene expression after adenoviral HL (Ad-HL) versus control GFP (Ad-GFP) infection." (PMID 21750705, 2011).
genetic disorder (9 papers, 2011 to 2024). "Familial LPLD is an autosomal recessive genetic disorder caused by loss-of-function mutations in LPL gene encoded lipoprotein lipase enzyme." (PMID 31608113, 2019). "LPL deficiency, a rare genetic disorder, results in decreased or absent LPL enzyme activity." (PMID 38521668, 2024). "Familial chylomicronemia which a rare genetic disorder related to reduced or absent lipoprotein lipase activity." (PMID 35242310, 2022). "Studies have shown that dyslipidemic subjects without genetic disorders present higher Apo CII levels (7.0 mg/dl) than normolipidemic subjects (3.0 mg/dl), which results in a disturbance of the Apo CII/LPL balance." (PMID 23241455, 2012).
heart disease (5 papers, 2006 to 2025). "People with both the Asp9Asn and T(-93)G mutations have been shown to have an increased risk of cardiac disease and decreased LPL activity in some studies." (PMID 25657638, 2014). "The other implication of the reported findings is that clinical trials will be required to enhance LPL activity and cardiac function in T2D patients with heart diseases using VEGF-B-based therapies." (PMID 41373652, 2025). "Reduced LPL activity culminates in the accumulation of lipids in cardiac tissues, thereby crippling mitochondrial function and encouraging oxidative stress, hence accelerating the development of heart disease." (PMID 41373652, 2025).
myopathy (5 papers, 2022 to 2025). A disease of the muscle in which the muscle fibers do not function properly. "However, higher levels of LPL expression resulted in severe myopathy and premature death of the transgenic mice due to a fatal accumulation of fatty acids." (PMID 35456470, 2022).
neurodegenerative disease (5 papers, 2020 to 2025). A disorder of the central nervous system characterized by gradual and progressive loss of neural tissue and neurologic function. "Although the function of LPL in the microglial response to neurodegenerative disease is not well understood, LPL polymorphisms are been implicated in disease risk, such as an association with AD risk." (PMID 34122343, 2021). "Other significantly downregulated genes included TREM2 and LPL, both highly expressed in microglia, and known to be involved in neurodegenerative diseases like AD through their function in regulating microglia lipid homeostasis as well as immune function." (PMID 41333389, 2025). "Since then, we have learned that LPL plays a critical role in lipoprotein processing throughout the body, which impacts the development of several cardiometabolic and neurodegenerative diseases." (PMID 35911520, 2022). "While associations with LPL polymorphisms and AD have been reported, there have been no reports (at the time of publication of this manuscript) that link LPL mutations with any other neurodegenerative disease." (PMID 33172164, 2020). "Hence, methods that can accurately quantify both circulating LPL, and the activity and abundance of LPL in a range of tissues and cells are much needed to further understand LPL biology, and to develop LPL-targeted strategies that can ameliorate cardiometabolic and neurodegenerative disease." (PMID 35911520, 2022).
inflammation (3 papers, 2023 to 2025). Aberrant reaction of the microcirculation characterized by movement of fluid and leukocytes from the blood into extravascular tissues. "The reduction in ANGPTL8 levels could indicate altered lipid metabolism, where LPL activity is deregulated, leading to an accumulation of free fatty acids and exacerbating pancreatic inflammation." (PMID 40282999, 2025).
kidney disease (3 papers, 2011 to 2014). "Severe kidney disease results in retention of uremic toxins that inhibit key enzymes for lipid breakdown such as lipoprotein lipase (LPL) and hepatic lipase (HL)." (PMID 24784324, 2014). "In animal models of kidney disease, significant reduction of LPL activity, mRNA level or protein mass is observed in the cardiac muscle, skeletal muscle and adipose tissues." (PMID 21762526, 2011). "The role of renal lipoprotein lipase (LPL) per se in kidney diseases is still controversial and obscure." (PMID 21762526, 2011). "On the contrary, there are many reports that LPL expression and activity in the heart, skeletal muscle, and adipose tissues are suppressed in humans and experimental animals with kidney disease." (PMID 21762526, 2011). "In view of the strong connection between LPL and kidney disease, however, it is surprising that there are few direct studies on the role of renal LPL." (PMID 21762526, 2011).
hematologic malignancies (2 papers, 2017 to 2022). "Recently the MYD88 mutation has been emerged as a hallmark of WM/LPL, implicating in its diagnosis, management, and treatment.1 patient with LPL was diagnosed with IgG4-associated disease 7 years after the diagnosis of hematological disease." (PMID 36172352, 2022).
respiratory diseases (2 papers, 2021). "DAPK1-IT1 has been reported to regulate cholesterol metabolism and inflammatory response in macrophages and promotes atherogenesis by sponging miR-590-3p and regulating LPL (lipoprotein lipase), and possibly linked to respiratory diseases." (PMID 34422899, 2021).
infectious disease (1 paper, 2022). A disorder directly resulting from the presence and activity of a microbial, viral, or parasitic agent in humans. "Triglyceride is usually degraded by lipoprotein lipase to produce free fatty acids, that may activate the nuclear factor-κB (NF-κB) role in the inflammatory response and resulting infectious diseases in kidney transplantation recipients." (PMID 36117592, 2022).
neurological diseases (1 paper, 2025). "The limited number of studies investigating LPL in the context of inflammation have primarily focused on cardiovascular and neurological diseases, where LPL exhibits proinflammatory effects by modulating immune cell responses and macrophage activity in the arterial wall." (PMID 40102905, 2025).
prostate (1 paper, 2025). "However, the significance of LPL loss may be misinterpreted due to its co-deletion with NKX3.1, a well-established event in prostate carcinogenesis." (PMID 40563400, 2025).
LPL also shares sentences with these, for which no sentence is quoted: non-alcoholic steatohepatitis (8 papers); Waldenström macroglobulinemia (7); inflammatory bowel disease (3); liver failure (3); metabolism (3); osteoporosis (3); acromegaly (2); aneurysm (2); bacterial infection (2); benign prostatic hyperplasia (2); Breast disease (2); colitis (2); Combined hyperlipidemia (2); endocrine disorders (2); follicular lymphoma (2); Hepatosplenomegaly (2); Hypoinsulinemia (2); Lymphadenopathy (2); mantle cell lymphoma (2); marginal zone lymphoma (2); monoclonal gammopathy (2); morbid obesity (2); peripheral artery disease (2); psoriasis (2); respiratory distress syndrome (2); unstable angina (2); acute liver failure (1); acute myeloid leukemia (1); adenocarcinoma (1); age-related macular degeneration (1).
A further 95 diseases each share a sentence with LPL in 1 paper.